VWF (von Willebrand factor)
Diseases named in the same sentence as VWF in open-access papers (continued):
Sharing a sentence is not in itself a finding about the gene and the disease.
melanoma (33 papers, 2011 to 2025). A malignant, usually aggressive tumor composed of atypical, neoplastic melanocytes. "Previous studies in mouse and human melanoma showed that vWF plays a key role in promoting cancer‐associated platelet aggregation, which is in line with results from studies showing increased platelet aggregation in patients with various types of cancer." (PMID 39760182, 2025). "Increased levels of pro-coagulant factors such as vWF ag or factor VIII:C correlated with an increased risk of cancer recurrence in melanoma patients treated with ICI in the adjuvant setting." (PMID 39487855, 2024). "Specifically, using a VWF-deficient murine model following the injection of B16-BL6 murine melanoma cells or Lewis lung carcinoma (LLC) cells, VWF was found to play a protective role against tumour cell dissemination by inducing apoptosis of metastatic cells." (PMID 33571850, 2021). "Among 366 melanoma cases from TCGA provisional, the somatic mutation rates ofFVIII,VWF, andADAMTS13in tumor cells were 15, 14, and 5%, respectively." (PMID 29152610, 2017). "Our previous studies have shown that blocking luminal VWF fiber formation is associated with tumor weight reduction and survival benefits in a ret transgenic mouse model of malignant melanoma, providing evidence of a pro-metastatic role for VWF." (PMID 27602496, 2016). "For instance, FBG and VWF deficiency respectively decreases and increases the metastatic potential of a lung carcinoma and a melanoma in mouse models." (PMID 24023955, 2013). "Here, we used in vitro settings and mouse models to examine malignant melanoma progression, and we used mice deficient in VWF (VWF −/−) and ADAMTS13 (A13 −/−) to evaluate whether VWF affects cancer-associated VTE and the formation of lymphatic and hematogenous metastases." (PMID 27602496, 2016). "•Proteins linked to melanoma development (PRG4, APOC4, SERPIND1, VWF, TNC and PLG) were identified in the plasma-derived EVs of patients with melanoma." (PMID 39405606, 2024). "Proteins (APOC4, PRG4, PLG, TNC, VWF and SERPIND1) and metabolites (lyso PC a C18:2, PC ae C44:3) previously associated with melanoma pathogenesis were identified as relevant in differentiating between disease stages." (PMID 39405606, 2024). "VWF is not only a mediator of platelet adhesion but has also recently been described as a mediator of metastasis in melanoma, as well as other malignancies." (PMID 39405606, 2024). "Integrin ανβ3 is expressed on EC and several malignancies, such as melanoma, glioma, ovarian and breast cancer, and mediates cancer cell adhesion to EC and also interaction with both VWF and platelets." (PMID 39282473, 2024). "Endothelial cell activation followed by vWF fiber formation was found to be the main culprit of platelet aggregation in malignant melanoma vasculature." (PMID 35814405, 2022). "VWF knockout mice have increased the pulmonary metastatic burden in mouse models of metastatic Lewis-lung carcinoma and melanoma." (PMID 35327035, 2022). "A static cell adhesion model demonstrated that binding of VWF to B16-BL6 melanoma cells was mediated by αvβ3 integrin expressed on the tumour cell surface." (PMID 33571850, 2021). "All these results showed that CDK4 or VWF inactivation inhibits the proliferation, migration, and invasion of melanoma." (PMID 34582363, 2021). "In the present study, the expression of KIT and VWF in the melanoma metastasis samples significantly increased." (PMID 34582363, 2021). "The results of this study showed that the PI3K-Akt signaling pathway and the key genes CDK2, CDK4, KIT, and VWF promoted the proliferation and metastasis of melanoma, and they were significantly related to the prognosis of patients with melanoma." (PMID 34582363, 2021). "The TMOD3/RAI14/VWF axis interacts with the cytoskeleton in prostate cancer, and Liu and colleagues revealed that cell migration and the invasion of melanoma was impaired by RAI14 depletion via regulating the AFAP1-AS1/miR-653-5p/RAI14 axis." (PMID 32957082, 2020).
melanoma (continued). "VWF strings were detected in human malignant melanoma tissues anchored at the microvessel surface of the tumor, promoting cancer progression." (PMID 27797778, 2017). "The specific VWF staining was detected in the vascular endothelium within the melanoma tissues (arrowheads)." (PMID 29152610, 2017). "Significantly elevated levels of angiopoietin-2 and soluble P-selectin (stored in WPBs adjacent to VWF) confirmed the melanoma cell supernatant-induced activation of HUVECs and the ability of Tinzaparin to inhibit EC activation." (PMID 27602496, 2016). "This study describes an in vitro melanoma cell-induced VWF release and an in vivo formation of luminal fibers in tumor microvessels." (PMID 27602496, 2016). "ELISA analysis indicated that Ret melanoma cell supernatants increased VWF exocytosis from HUVECs and LECs." (PMID 27602496, 2016). "In line with the results of previous studies, the anti-VEGF-A-antibody Bevacizumab significantly reduced VEGF-A- and melanoma-mediated VWF release by approximately 40%, thus confirming the essential role of VEGF-A in EC activation." (PMID 27602496, 2016). "Interestingly, opposite results have been found in VWF deficient mice, showing that the initial establishment of metastatic foci using B16-BL6 melanoma cells increased in VWF deficient mice comparing with the wild-type mice." (PMID 39282473, 2024). "In mouse models, human blood samples, and melanoma tissue samples, the tumor cell-mediated release of von Willebrand Factor (vWF) from platelets and endothelial cells resulted in platelet aggregation and accelerated deposition of thrombin within the melanoma vasculature." (PMID 39114075, 2024). "CD31 and VWF were markedly reduced in melanomas of Colec11–/– mice compared with WT mice." (PMID 36883567, 2023). "Evidence to support the VWF promoting tumor metastasis comes from in vivo mouse experiments, which demonstrate that VWF inhibition results in significantly reduced metastasis in disseminating colon carcinoma, melanoma, Lewis-bladder cancer, gastric cancer and thyroid cancer." (PMID 35327035, 2022). "In melanoma cells with or without BRAFV600E inhibitor resistance, inhibiting the expression of CDK2, CDK4, KIT, and VWF may become a new choice to inhibit the progression of melanoma." (PMID 34582363, 2021). "Moreover, under condition of shear stress, blocking αvβ3 integrins inhibited VWF-mediated melanoma cell adhesion." (PMID 33571850, 2021). "EdU, transwell, and wound healing assays were conducted to verify whether CDK4 or VWF inactivation can affect the proliferation, migration, and invasion of melanoma cells." (PMID 34582363, 2021). "In the GSE32474 dataset, the expression levels of CDK2, CDK4, KIT, and VWF in the melanoma metastasis group were significantly higher than those in the melanoma primary focus group (t = 2.616, 2.244, 2.137, and 2.570, respectively; logFC = 1.206, 0.240, 1.573, and 0.168, respectively; p < 0.05)." (PMID 34582363, 2021). "Local injection of RAGE-aptamer adjacent to the tumor dramatically decreased the growth of G361 melanoma in nude mice, which was associated with reduced expression of CML, RAGE, nitrotyrosine, VEGF, CD31, and von Willebrand factor, markers of endothelial cells in G361 tumors." (PMID 31565056, 2019). "Von-Willebrand Factor (VWF) also plays a role in platelet aggregation and recruitment of platelets to the vascular endothelium as demonstrated in patients with melanoma and mouse models of melanoma." (PMID 29164134, 2017). "To investigate the role of EC activation and VWF formation in hematogenous tumor dissemination, we used a second mouse model based on the induction of lung metastases by intravenous (i.v.)injection of Ret melanoma cells." (PMID 27602496, 2016). "Indeed, we detected a substantial increase in EC activation and luminal VWF fiber formation in metastasis-free livers, brains and lungs, which are the most frequent target organs for malignant melanoma metastasis." (PMID 27602496, 2016).
melanoma (continued). "The critical role of VWF in tumor progression is further supported by previous studies demonstrating that melanoma cells are able to stimulate undamaged ECs via tissue factor and subsequent thrombin generation, thereby stimulating the endothelial protease activator receptor-1 (PAR-1)." (PMID 27602496, 2016). "Interestingly, the mice showed a strong increase in lung metastases, thus confirming a unique role of intraluminal VWF fibers in the extravasation of melanoma cells." (PMID 27602496, 2016). "Moreover, we have recently observed VWF fibers in the tumor vasculatures of melanoma patients and ret transgenic mice (a mouse model characterized by spontaneous melanoma development)." (PMID 27602496, 2016). "Our own in vitro studies have revealed that melanoma cells activate vascular endothelial cells (ECs), thus resulting in the exocytosis of Weibel-Palade bodies (WPBs) and the release of procoagulatory, ultra-large von Willebrand factor (ULVWF) multimers from intact ECs." (PMID 27602496, 2016). "For the hazard analysis of baseline vWF ag and factor VIII:C on RFS and OS the cohort was complemented with 6 melanoma patients before start of adjuvant therapy (55–83 years of age, mean 71.8 years)." (PMID 39487855, 2024). "In melanoma vasculatures, CD42+ platelet aggregates were also seen bound to intravascular vWF fibres, due to an endothelial glycocalyx shedding-dependent process." (PMID 35100311, 2022). "Treatment of a transgenic mouse model of melanoma with tinzaparin, a specific low molecular weight heparin (LMWH), resulted in reduced tumor vascular accumulation of VWF, reduced tumor growth, angiogenesis and metastasis." (PMID 35327035, 2022). "There is indirect evidence for VWF-mediated angiogenesis in an ADAMTS13−/− mouse model of melanoma, where increased intraluminal VWF deposition induced by melanoma directly correlated with increased tumor vessel density." (PMID 35327035, 2022). "Survival analysis showed that the OS rate of patients with melanoma in the high expression group of KIT and VWF was significantly reduced." (PMID 34582363, 2021). "The results of the survival analysis of patients with melanoma in TCGA demonstrated that the high expression of CDK2, CDK4, KIT, and VWF significantly reduced the survival rate of patients." (PMID 34582363, 2021). "To determine the in vivo relevance of VWF fibers in blood vessels, we analyzed primary skin tumors obtained from intradermal injections of Ret or B16F10 melanoma cells." (PMID 27602496, 2016). "The corresponding quantification revealed that only 2.6 ± 1.8% of vessels in the healthy skin contained VWF fibers; this was significantly increased to 22.0 ± 2.3% in the Ret tumor tissue and to 27.6 ± 2.0% in B16F10 melanomas." (PMID 27602496, 2016). "Von Willebrand factor, CD34, CD31, Ulex europaeus agglutinin 1, vascular endothelial growth factor, melanocytic markers (such as S100), human melanoma black-45, melanoma antigen and cytokeratins all are useful for diagnosis and differential diagnosis." (PMID 24067058, 2013). "The combination of the identified proteomic and metabolomic datasets revealed the optimal features for differentiation were 2-proteins, VWF and SERPIND1 which classified the samples between those with metastatic and primary melanoma with 79.41 % accuracy (Acc > NIR, p = 0.049)." (PMID 39405606, 2024). "We found a therapeutic potential of R/P-cGNS on melanoma cells in particular; the melanoma cancer cell line B16-BL6 is reported to be effective in the treatment of curcumin and also to have a high expression level of vWF, which is the main target of PLTs." (PMID 32158752, 2020). "The role of VWF and its cleaving protease ADAMTS13 in melanoma metastasis is much less clear." (PMID 29152610, 2017). "The non-immune cell clusters were made up of melanoma cells (MLANA, PMEL, MITF, DCT), endothelial cells (VWF, PECAM1) and fibroblast cells (COL1A1, COL3A1)." (PMID 36433984, 2022).
atrial fibrillation (29 papers, 2014 to 2025). A disorder characterized by an electrocardiographic finding of a supraventricular arrhythmia characterized by the replacement of consistent P waves by rapid oscillations or fibrillatory waves that vary in size, shape and timing and are accompanied by an irregular ventricular response. "Although aortic valve replacement is known to mitigate bleeding risk by correcting shear stress-induced von Willebrand factor abnormalities, the patient's frailty, atrial fibrillation, and preference for conservative management complicated decision-making." (PMID 41978710, 2025). "Low ADAMTS-13 and high VWF have been associated with cardiovascular disease and atrial fibrillation (AF)." (PMID 37255854, 2023). "The LA subregion dysregulated genes are strongly associated with atrial fibrillation, vWF-related diseases, tachycardia, and CVD prevalence, whereas DCM associated genes are only significantly enriched in LV altered genes." (PMID 34088950, 2021). "The 41 Heart- and RA-Enriched genes were highly associated with atrial fibrillation and vWF-related diseases." (PMID 34088950, 2021). "Further adjustment for atrial fibrillation, IL-6, vWF and FEV1 attenuated the association but risk remained significantly reduced in the top quintile (≥ 0.87 mmol/l) compared with the lowest quintile [HR 0.62 (0.40, 0.97)]." (PMID 29663176, 2018). "Further research revealed strong associations between atrial fibrillation and both phenotypes; increased levels of vWF associate with incidence of atrial fibrillation, and incidence of atrial fibrillation associates with increased hippocampal atrophy." (PMID 24460644, 2014). "•Low ADAMTS-13 predicted death, and low VWF was associated with new-onset atrial fibrillation." (PMID 37255854, 2023). "The major findings from our analysis of the HFrEF altered genes and GWAS traits included strong association between LA-dysregulated genes and atrial fibrillation, vWF-related diseases, tachycardia, and CVD prevalence, whereas DCM-associated genes were significantly enriched in LV altered genes." (PMID 34088950, 2021). "Moreover fibrinogen and vWF-VIII have been associated with incident atrial fibrillation (AF), a major risk factor for HF." (PMID 28043678, 2017). "Therefore, atrial fibrillation could play an important role in the association between VWF and ADAMTS13 and mortality in dialysis patients." (PMID 34134634, 2021). "D-dimer and vWF were significantly and positively associated with NT-proBNP (a marker of neurohormonal activation and left ventricular wall stress) even after adjustment for age, lifestyle characteristics, renal dysfunction, atrial fibrillation (AF) and inflammation (C-reactive protein)." (PMID 28043678, 2017). "Elevated vWF levels were also linked to major adverse cardiac events, suggesting a prognostic role for higher vWF levels in atrial fibrillation patients." (PMID 40283058, 2025). "Recently this increase in vWF was also demonstrated in patients undergoing minimally invasive surgery for atrial fibrillation." (PMID 34957252, 2021). "Dialysis patients have highly increased risks of atrial fibrillation and VWF and ADAMTS13 have been associated with worse outcomes in patients with atrial fibrillation." (PMID 34134634, 2021). "Alterations in both VWF and ADAMTS13 levels have also been implicated in patients with atrial fibrillation (AF)." (PMID 34564132, 2021). "Several prothrombotic biomarkers, such as D-dimer, von Willebrand factor, and beta-thromboglobulin are present in higher concentrations in patients affected by atrial fibrillation (AF)." (PMID 32684980, 2020). "Through this analysis, PHPN exposed atrial fibrillation phenotype as a key connector between VWF and HA even though none of these three PTs share any common genetic risk factors, as reported in the GWAS catalogue, but all three phenotypes shared a common biological pathway." (PMID 24460644, 2014).
atrial fibrillation (continued). "In the first of these studies, a significant increase in the expression of vWF in the endocardium of atrial appendages was identified in human patients with a variety of congenital and acquired heart diseases irrespective of the presence of atrial fibrillation." (PMID 33925795, 2021). "Finally, we could not investigate the association between VWF and ADAMTS13 and mortality in a subgroup of patients with atrial fibrillation, since we had no information about the presence of atrial fibrillation in our cohort." (PMID 34134634, 2021).